ICAM1 (intercellular adhesion molecule 1)
Diseases named in the same sentence as ICAM1 in open-access papers (continued):
Sharing a sentence is not in itself a finding about the gene and the disease.
cardiovascular disease (continued). "The infiltration of immune cells is due to up-regulation of adhesion molecules including ICAM-1 and VCAM-1 which contribute to several chronic inflammatory diseases including cardiovascular diseases." (PMID 26173590, 2015). "We investigated the role of four thrombosis genes: coagulation factor V (F5), intercellular adhesion molecule 1 (ICAM1), protein C (PROC), and thrombomodulin (THBD) in cardiovascular diseases." (PMID 17677000, 2007). "Notable, in the Dallas Heart Study (involving 2,442 participants without prior cardiovascular disease) only soluble ESAM, but not soluble ICAM-1 or soluble VCAM-1, levels were associated with incidents of atherosclerotic and total cardiovascular disease." (PMID 39740345, 2025). "This intricate interplay underscores the pivotal roles of ICAM-1 and VCAM-1 in cardiovascular pathophysiology and accentuates their potential as therapeutic targets for mitigating cardiovascular disease progression, particularly through the modulation of NF-kB signaling." (PMID 39513877, 2024). "Notable, in the Dallas Heart Study, involving 2442 participants without prior cardiovascular disease soluble ESAM, but not soluble ICAM‐1 or soluble VCAM‐1, levels were associated with incident atherosclerotic and total cardiovascular disease." (PMID 36946064, 2023). "Previous studies have confirmed that vascular endothelial inflammatory factors IL-1β, TNF-α, and adhesion factors ICAM-1 and VCAM-1 are essential markers of vascular endothelial injury and dysfunction, which can predict cardiovascular disease, and correlate with the severity of ACS." (PMID 35302437, 2022). "We had previously studied the expression of ICAM-1 with respect to platelet EVs using the same cohort, as ICAM-1 has been reported to play a crucial role in the pathophysiology of cardiovascular diseases by activating inflammatory responses at the endothelial level." (PMID 35850658, 2022). "Interestingly, although KLF2 is known to suppress VCAM-1 and ICAM-1 expression under physiological conditions, we observed increased VCAM-1 mRNA expression, consistent with a proinflammatory endothelial phenotype commonly observed in cardiovascular disease." (PMID 41562845, 2026). "Also genes such as ICAM1, MCP1, IL6 or IL1β of which expression is controlled by nuclear factor kappa B (NF-κB) and of which transcriptional activation is critical in a number of pathologies, including cardiovascular diseases, are differentially expressed in the presence of polyphenols." (PMID 24763279, 2014).
bacterial infection (26 papers, 2006 to 2025). "Mice with bacterial infection can also boost ICAM-1+ neutrophils, which was associated with neutrophil reverse transendothelial cell migration." (PMID 40568695, 2025). "In particular, FoxO1 promotes the transcription of CCR7 and intercellular adhesion molecule-1 (ICAM-1), both of which are critical for the DC-mediated stimulation of T and B lymphocytes in response to bacterial infection." (PMID 36233176, 2022). "Several studies have previously shown that human pleural mesothelial cells upregulate their ICAM-1 expression and serve as chemokine sources in response to bacterial infection, thus directly participating in the recruitment of monocytes and CD4+ T cells." (PMID 35418979, 2022). "There was an increase in the percentage of innate immune system cells such as CD68+ macrophages, ICAM-1-expressing cells, and CD54+ dendritic and endothelial cells, which is a normal response to bacterial infection." (PMID 35625758, 2022). "Multiple studies have shown ICAM-1 production is induced in host cells following various bacterial infections including M. tb, M. avium, S. pneumoniae and Salmonella, although the pathways leading to its expression were not defined in these studies." (PMID 32463840, 2020). "On the contrary, increased ICAM-1 expression in ECs has also been suggested to result in increased neutrophil adherence to those cells and induce innate defense against bacterial infection suggests a protective mechanism against microbial translocation." (PMID 22291924, 2012). "Several elegant studies have demonstrated a pro-inflammatory reaction of ependyma and choroid plexus epithelia in response to bacterial infection including the expression of tumour necrosis factor-α and ICAM-1 to facilitate neutrophil invasion." (PMID 16948860, 2006). "We next assessed whether bacterial infection triggered prominent changes of ICAM-1 mRNA expression; thus, trout were immersed with F. columnare G4 strain marked with GFP." (PMID 34489953, 2021). "Taken together, these results indicated that ICAM-1 might play an important role in mucosal immune response to bacterial infection." (PMID 34489953, 2021). "In conclusion, an induction of ICAM-1 expression by bacterial infection might indicate an important mucosal immune role of this receptor during bacterial infection, but the mechanism played by ICAM-1 remains to be understood." (PMID 34489953, 2021). "We hypothesize that ICAM1 antagonists could also be repurposed against viral and bacterial infections." (PMID 24086587, 2013). "We suggest a likely role of ICAM1 in bacterial infections as well." (PMID 24086587, 2013). "The interaction of β2 integrin expressed on neutrophil and ICAM-1 (intercellular cell adhesion molecule-1) presented on inflammatory vascular endothelial cells plays an important role in adhesion and transmigration of neutrophil to the bacterial infection site." (PMID 37061741, 2023). "While the role of ICAM-1 during bacterial infections has been investigated using ICAM-1-/- mice, little is known about ICAM-1’s function in promoting an antibacterial response within infected host cells." (PMID 32463840, 2020). "Moreover, P. gingivalis attenuated the production of IL-8 and intercellular adhesion molecule-1 (ICAM-1) in epithelial cells and blocked neutrophil migration across intact epithelial barriers, which impairs the ability of the host to detect bacteria and contributes to sustained bacterial infection." (PMID 30040860, 2018). "In the context of bacterial infections, most published studies have focused on ICAM-1 expression in epithelial or endothelial cells, rather than in leukocytes." (PMID 40137696, 2025). "Bacterial infections are frequently detected around the portal tracts of PSC patients and elevated serum endotoxin can increase the expression of adhesion molecules such as VCAM-1 and ICAM-1." (PMID 37820623, 2023).
bacterial infection (continued). "Our findings that ICAM-1 expression is diminished in BMMs that lack RIG-I or MAVS expression following an M. avium infection suggest a link between RNA sensing pathways and an immune response to this bacterial infection." (PMID 32463840, 2020). "In addition to the increase of inflammatory cytokines, the activation of endothelial cells by LPS was also indicated by the abundant expression of molecules such as ICAM‐1 and VCAM‐1 which are known to mediate the immune response in endothelial cells in response to bacterial infections." (PMID 29210175, 2018).
retinopathy (23 papers, 2009 to 2025). "The association of VEGF and ICAM-1 with severity of retinopathy was analyzed using multiple regression analysis." (PMID 23922493, 2013). "Meanwhile, they reduced the expression of VEGF and ICAM1 in retinopathy and increased the expression of Bcl-2 and PEDF." (PMID 34691233, 2021). "Increased ICAM-1, VCAM-1, and E-selectin are associated with nephropathy, retinopathy, and cardiovascular disease in both T1DM and T2DM." (PMID 24688225, 2014). "The ICAM-1 level has been shown to be increased in the diabetic retina, even in the early stages of retinopathy." (PMID 24688225, 2014). "The current study was undertaken to correlate the serum levels of VEGF and ICAM-1 with the level of retinopathy and the grade of ELM and inner segment-outer segment (IS-OS) junction disruption in type 2 DM." (PMID 23922493, 2013). "A significant association was found between the severity of retinopathy and VEGF (OR=3.91, 95% CI 1.023–14.97, p<0.05) and ICAM-1 (OR=3.98, 95% CI 1.04–15.27, p<0.05)." (PMID 23922493, 2013). "Upregulation of ICAM-1 is likely relevant to the pathogenesis of I-R-induced retinopathy since the level of ICAM-1 expression regulates the degree of leukocyte recruitment in inflammation." (PMID 19626134, 2009). "These pathways could lead to osmotic vascular damage and retinopathy by activation of mitogen activated protein kinases (MAPKs), inducing the production of ICAM-1 and VCAM-1, and the breakdown of the vascular junction proteins." (PMID 38790059, 2024). "Hypothesizing that control over ICAM-1 expression should prevent the earliest stages of retinopathy, the authors applied small-interfering RNA (siRNAs) through a hydrodynamics-based transfection technique (HT) and intravitreal injection (IV) to a murine retina in vivo." (PMID 23028203, 2012). "Intercellular adhesion molecule-1 (ICAM-1 or CD54) and nitric oxide synthase 2 (NOS2) are two molecules involved in retinal disorders." (PMID 19626134, 2009). "A study involving 37 patients with SCR, 34 SCD patients without retinopathy, and healthy found significantly lower soluble intercellular adhesion molecule-1 (sICAM-1) levels and higher pigment epithelium-derived factor (PEDF) levels in SCR patients." (PMID 38976013, 2024).
nephropathy (18 papers, 2011 to 2025). A nonspecific term referring to disease or damage of the kidneys. "We apply high-plex spatial molecular imaging using the CosMx platform to human kidney disease, leveraging the single cell resolution to determine that it is specifically the ICAM1+ inflammatory PT cells that localize to the fibrotic niche." (PMID 40399382, 2025). "Increased glomerular expression of ICAM-1 is commonly observed in patients with renal diseases, including LN." (PMID 32910199, 2020). "The IL-8/CXCR1 signaling axis facilitates neutrophil recruitment and local inflammatory responses in kidney disease by enhancing the expression of intercellular adhesion molecule 1 (ICAM-1) and activating the p38 mitogen-activated protein kinase (MAPK) pathway." (PMID 40521043, 2025). "We further interrogated the adaptive PT cells in the KPMP Atlas, confirming the presence of an ICAM1+ subset that expresses the same inflammatory gene signature, suggesting that this PT cell subset is found in other kidney diseases." (PMID 40399382, 2025). "Meanwhile, urinary ICAM-1 levels increased in patients with kidney diseases." (PMID 30868076, 2019). "In summary, we have generated a comprehensive multiomic atlas of the cellular heterogeneity in human kidney disease and identified druggable signalling pathways by which an ICAM1+ inflammatory tubular cell subset may mediate tubulointerstitial inflammation and fibrosis." (PMID 40399382, 2025). "NF-κB, a transcription factor, is closely involved in the regulation of renal disease progression, as it promotes the transcription of pro-inflammatory cytokines, such as TNF-α, IL-6, and ICAM-1." (PMID 35295738, 2021). "Elegant studies from the Fernandes laboratory have related the delayed onset and decreased severity of renal disease exhibited in fish oil-fed NZBWF1 mice to reduced IL-1β, TNF-α, TGFβ1, ICAM-1 and fibronectin expression and increased expression of antioxidant enzymes." (PMID 27513935, 2016).
neurological diseases (15 papers, 2012 to 2025). "We propose ICAM-1 signaling cascade as a target for developing new therapeutic strategies against TBI related neurologic diseases." (PMID 34135004, 2021). "ICAM1, also known as CD54, may increase neprilysin levels, essential to treat neurological diseases, including PD." (PMID 37089789, 2023). "Cell adhesion molecules, including ICAM-1 and VCAM-1, play an important role in neurological diseases." (PMID 35208996, 2022). "Several reported studies on the role of VEGF-A in the induction of ICAM-1 in different neurologic disorders led us to analyze the role of VEGF-A and its receptor VEGFR-2 in the induction of ICAM-1 in our in vitro model." (PMID 34135004, 2021). "IVIG is suggested to achieve therapeutic effects in GBS via reduction of IL-1, intercellular adhesion molecule-1, and especially TNF-α, which is significantly higher in GBS than other neurological disease controls." (PMID 34539561, 2021). "Taken together, the ability of ICAM-1 targeted liposomes to bind ICAM-1 under these harsh conditions might allow this contrast agent to visualize ICAM-1 in a variety of cardiovascular and neurological diseases using in vivo MR-imaging." (PMID 22716048, 2012).
kidney (13 papers, 2011 to 2026). "In this study, CC inhibited the increased expression of MCP-1, IL-6, IL-1β, COX-2, ICAM-1, and F4/80 in AD-induced kidney injury." (PMID 37513959, 2023). "Collectively, our results provided novel insight into the downstream mechanism of the IL-6 signaling pathway in PM-induced aorta inflammation, that is, ICAM-1 and VCAM-1-dependent monocyte adhesion." (PMID 34336088, 2021). "The administration of green tea extract prevents the release of systemic proinflammatory cytokines, neutrophil infiltration, and the expression of IL-6 and intercellular adhesion molecule-1 (ICAM-1) after hemorrhage/resuscitation-induced liver injury." (PMID 34899956, 2021). "Over-expression of ICAM-1 and P-selectin by vascular endothelium of the ischemic kidney has been demonstrated to play a major patho-physiological role in the development of renal dysfunction." (PMID 29755348, 2018). "I/R‐induced kidney injury is also prevented in models of neutrophil depletion by administration of antibodies to intercellular adhesion molecule 1 (ICAM‐1) and by ICAM‐1 knockout." (PMID 38241017, 2024). "Meanwhile, the expressions of GGT-1, ICAM-1 and VCAM-1 were significantly decreased in the whole aorta plaques." (PMID 25326709, 2014). "Berberine increased IKBα and decreased NF-κBp65 protein levels in diabetic mouse kidney, as well as inhibiting renal AGE generation and downregulating TGF-β1, ICAM-1, and VCAM-1 protein expression." (PMID 23935673, 2013). "Interestingly, according to our results, ICAM1 is activated, among others, by LPA, indicating potentially common mechanisms between LPA effects and kidney pathologies." (PMID 35806457, 2022). "Furthermore, ROCK2 enhances the expression of adhesion molecules such as intercellular adhesion molecule-1 (ICAM-1) and vascular cell adhesion molecule-1 (VCAM-1) in endothelial cells, fostering a proinflammatory microenvironment that promotes leukocyte infiltration and perpetuates kidney injury." (PMID 41311514, 2026).
vasculopathy (12 papers, 2013 to 2025). "We have previously shown that cross-linking ICAM-1 with monoclonal antibodies leads to pro-inflammatory activation of human endothelial and vascular smooth muscle cells and that cardiac transplant recipients with transplant associated vasculopathy make antibodies directed against ICAM-1." (PMID 23685129, 2013). "Our study demonstrates that platelet-derived miR-223 at least in part contributes to KD vasculopathy by targeting ICAM-1." (PMID 35983051, 2022). "Soluble adhesion molecule markers, such as ICAM-1, ICAM-3, and VCAM1, and inflammatory cytokine and markers like neopterin have been used as possible biomarkers of vasculopathy in JDM." (PMID 37957619, 2023). "It appears, therefore, that ICAM-1+ macrophages, not endothelia, are involved in the ECM-associated vasculopathy." (PMID 25474413, 2014). "The activation of the Rho/ROCK pathway by ICAM-1 has been reported to initiate a positive feedback loop that could result in the expression of more ICAM-1 and the recruitment of more leukocytes and that subsequently lead to diverse vasculopathies." (PMID 35062347, 2022). "In the present study, pro- inflammatory molecules as ICAM-1 and VCAM-1 were markedly elevated in diabetic patients with PVD and had a negative correlation with A/BI in vasculopathy." (PMID 25287126, 2014).
adenocarcinoma (9 papers, 2007 to 2025). A common cancer characterized by the presence of malignant glandular cells. "Human adenocarcinoma (ADC)-derived A549 cells and mouse LLC cells expressed minimal surface ICAM-1." (PMID 23565296, 2013).
infectious disease (9 papers, 2014 to 2025). A disorder directly resulting from the presence and activity of a microbial, viral, or parasitic agent in humans. "Soluble forms of cell surface molecules such as sE-selectin, intercellular adhesion molecule-1 (ICAM-1) and vascular cell adhesion molecule-1 (VCAM-1) are released from ECs after activation and are used as diagnostic and prognostic markers in infectious diseases." (PMID 26462910, 2015). "In fact, in infectious diseases dysregulation of numerous ADAM substrates such as junction molecules (e.g., E-cadherin, VE-cadherin, JAM-A), adhesion molecules (e.g., ICAM-1, VCAM-1, L-selectin), and chemokines and cytokines (e.g., CXCL16, TNF-α) has been observed." (PMID 33392273, 2020).
metabolic disorders (9 papers, 2014 to 2025). "Circulating inflammatory biomarkers such as CRP, IL-6, TNF-α, monocyte chemotactic protein 1 (MCP-1), intercellular adhesion molecule 1 (ICAM-1), vascular cell adhesion protein 1 (VCAM-1), and E-selectin have been associated with a variety of metabolic disorders and associated outcomes." (PMID 24911359, 2014). "In parallel, metabolic disorders products FFA and LPS bind to membrane protein receptors of ECs and monocytes, leading to increased secretion of vascular cell adhesion molecules (intercellular adhesion molecule 1 (ICAM-1), etc.)and E-selectin." (PMID 37904236, 2023). "VSURF selected immune markers that were positively correlated with the metabolic disease score included LBP, intercellular adhesion molecule 1 (ICAM-1), interleukin-16 (IL-16), IL-12, and granulocyte-macrophage colony-stimulating factor (GM-CSF)." (PMID 34006628, 2021). "Consistent with the previously reported role of inflammation in this relationship, age was positively correlated with 5 of the 14 immune measures that VSURF selected as important predictors of the metabolic disease score, including LBP, CRP, IL-6, ICAM-1, and SAA." (PMID 34006628, 2021). "Intercellular adhesion molecule-1 (ICAM-1), monocyte chemoattractant protein-1 (MCP-1), tumor necrosis factor-α (TNF-α), and plasminogen activator inhibitor-1 (PAI-1) are potent biological markers for the development of inflammatory and metabolic diseases which may include PCOS." (PMID 36793022, 2023).